GAP43 (growth associated protein 43)
Diseases named in the same sentence as GAP43 in open-access papers (continued):
Sharing a sentence is not in itself a finding about the gene and the disease.
neuroblastoma (31 papers, 2009 to 2025). Neuroblastoma (NB) is the most common solid, extracranial childhood tumor. "This was associated with elevated expression of neuroblastoma (e.g. Phox2b), sympatho-adrenal (e.g. Th), neural (e.g. Gap43), neural stem cell (e.g. Msi1) and neural crest cell markers (e.g. Tfap2b)." (PMID 37246217, 2023). "According to previous reports, the leaf extract of AC showed protective effects against high glucose-induced neurotoxicity and neurite outgrowth impairment in neuroblastoma cells via up-regulated expressions of teneurin-4 and growth-associated protein 43 (GAP43)." (PMID 39203863, 2024). "Fate 2, corresponding to cluster cIVS, exhibited increasing expression of neuronal function markers NPY, MAP2, GAP43, and GATA2, which are associated with differentiating neuroblastomas." (PMID 40448172, 2025). "SiCDKN3 upregulated protein levels of all the three differentiation markers that have been associated with neuroblastoma cell differentiation, NSE, βIII-tubulin and GAP43 proteins." (PMID 38356706, 2024). "We then demonstrated that CDKN3 knockdown increased expression of neuroblastoma molecular differentiation markers, neuron specific enolase (NSE), βIII-tubulin and growth associated protein 43 (GAP43)." (PMID 38356706, 2024). "We confirmed that the commonly used neuroblastoma MRD markers (including PHOX2B, TH, CHRNA3, GAP43) are rarely expressed in mesenchymal neuroblastoma cell lines." (PMID 39722049, 2024). "Recent study has shown that GAP43 serves as a specific biomarker of relapsed or refractory neuroblastoma." (PMID 33402155, 2021). "When BM samples are evaluated by a set of five markers (CHRNA3, DDC, GAP43, PHOX2B, and TH), unfavorable outcome in localized neuroblastoma patients is associated with the detection of more than one positive-marker." (PMID 31214500, 2019). "MRD detection in BM samples evaluated by a set of five markers (CHRNA3, DDC, GAP43, PHOX2B, and TH) was associated with poor outcome in patients aged over 1 year with stage 4 neuroblastoma." (PMID 31214500, 2019). "Triple PIM/PI3K/mTOR inhibition induced differentiation of neuroblastoma cells, increasing the expression of the sympathetic neuronal marker Gap43 and promoting neurite outgrowth." (PMID 31310053, 2019). "GAP-43 overexpression strikingly potentiated the action of NGF on neurite initiation and regeneration in PC12 cells while GAP-43 inhibition prevented the neuritogenesis of neuroblastoma cells." (PMID 26840295, 2016). "Inhibition of MYCN expression in vitro results in maturation of neuroblastoma cell lines, with neurite outgrowth and upregulation of the differentiation markers neurofilament and GAP43." (PMID 26222553, 2015). "Recent study has shown that GAP43 is responsible for the development of neuronal growth and axonal regeneration in normal nervous tissue, while serves as a specific biomarker of relapsed or refractory neuroblastoma." (PMID 33402155, 2021). "Given its specific expression in neurons, GAP43 is often used to differentiate between nerve sheath and non-nerve sheath neoplasms in the brain, and it also serves to detect minimal residual disease in neuroblastoma." (PMID 30419922, 2018). "Finally, we studied the distribution of Growth-Associated Protein 43 (GAP 43) expressing cells, which is a marker for axonal growth and an established marker for an early sympathetic neuronal phenotype in neuroblastoma." (PMID 20862257, 2010). "Withaferin A- and withanone-treated neuroblastoma cells may exhibit GAP-43 upregulation." (PMID 40427603, 2025).
neuroblastoma (continued). "Furthermore hypoxia, validated as predictor of poor outcome in neuroblastoma, was found to induce a shift from neuronal to chromaffin cell differentiation, with high expression of neuroendocrine markers and decrease in neuronal markers as GAP43." (PMID 29930753, 2018). "In human neuroblastoma cells, we showed ORY’s ability to stimulate neurite outgrowth, upregulating the expression of GAP43, BDNF, and TrkB genes." (PMID 39199215, 2024). "Mechanistically, we observed that in MYCN-amplified neuroblastoma cells, silencing of TFAP4 induces neurite outgrowth and upregulation of the neuronal marker GAP43." (PMID 29880876, 2018). "Here, neuroblastoma (NB) cell line subtypes were characterized according to embryonic peripheral nervous system development markers (GAP43, Phox2b, Sox10, c-kit, GD2, NF68, vimentin, S100β, calcyclin and ABCG2), morphological features, gene expression and differentiation potential." (PMID 19216736, 2009). "Each of these was supported by (i) the upregulation of KRT18, KRT19, E-cadherin, and downregulation of vimentin in breast carcinoma; (ii) increased levels of GFAP, MAP2, and PSD-95 in astrocytoma; and (iii) increased NeuN, GAP-43, and NF200 levels in neuroblastoma." (PMID 39859209, 2025). "We investigated the effects of TIR on markers of neuronal growth (CREB and BDNF), apoptosis (BAX/Bcl2 ratio) differentiation (pAkt, MAP2, GAP43, and AGBL4), and insulin resistance (GLUT1, GLUT4, GLUT3 and SORBS1) in a neuroblastoma cell line (SHSY5Y) exposed to normal and high glucose concentration." (PMID 38287296, 2024). "The biochemical differentiation profile of neuroblastoma cells overexpressing TMODs showed a significant increase of MAP2 and GAP43, mimicking then the “neuronal differentiation” obtained by retinoic acid, and an overall decrease of TH, DBH and CgA mRNA expression levels." (PMID 29930753, 2018).
Alzheimer disease (26 papers, 2012 to 2025). A progressive, neurodegenerative disease characterized by loss of function and death of nerve cells in several areas of the brain leading to loss of cognitive function such as memory and language. "AT(N) Alzheimer’s disease continuum group membership (P < 0.001), plasma NfL (P < 0.001) and CSF GAP-43 (P < 0.001) were negatively associated with episodic memory performance." (PMID 39995657, 2025). "Higher levels of growth-associated protein 43 were associated with worse memory in adults with Alzheimer’s disease." (PMID 39995657, 2025). "This concept is supported by the down-regulation of growth associated protein 43, which seems to play a pathologic role in the abnormal hyper-activation of hippocampal cells and the dysfunctional signal transduction seen in Alzheimer's disease." (PMID 23211425, 2012). "Growth-associated protein 43 may predict worse episodic memory performance in participants with greater Alzheimer’s disease pathology." (PMID 39995657, 2025). "Consistent with prior studies implicating synaptic dysfunction with core Alzheimer’s disease pathologies, we also found that an increase in CSF GAP-43 was associated with worse episodic memory performance specifically in older adults in the Alzheimer’s disease continuum group." (PMID 39995657, 2025). "This study shows that GAP-43, a marker of synaptic abnormality, is linked to faster tau spread, showing that synaptic changes may contribute to tau spreading in Alzheimer’s disease." (PMID 38172114, 2024). "This suggests that GAP-43-related synaptic changes are linked to faster Aβ-related tau spread across connected regions and that synapses could be key targets for preventing tau spreading in Alzheimer’s disease." (PMID 38172114, 2024). "As increased CSF GAP-43 concentration was associated to Alzheimer’s disease neuropathology and correlated with cognitive decline, it could be useful as an outcome marker in clinical trials for novel Alzheimer’s disease therapeutics." (PMID 30526557, 2018). "The slope of GAP-43 on episodic memory performance in the Alzheimer’s disease continuum group was significantly different from the slope in the no Alzheimer’s disease pathology group, which was not significant (P < 0.01)." (PMID 39995657, 2025). "Davidsson and Blennow reported a reduction of GAP-43 in the frontal cortex of early-onset and late-onset Alzheimer’s disease patients." (PMID 33578866, 2021). "In an earlier study, CSF GAP-43 was significantly elevated in Alzheimer’s disease patients compared to age-matched healthy controls and patients with frontotemporal dementia." (PMID 33578866, 2021). "There was a study to check GAP-43 levels in the early stage and late stage of Alzheimer’s disease and Parkinson’s disease when GAP-43 was mainly reduced." (PMID 34086836, 2021). "In a previous study of several dementia disorders, we have shown a specific increase in CSF GAP-43 in Alzheimer’s disease compared to several other neurodegenerative diseases." (PMID 30526557, 2018). "The transient increase of CSF GAP-43 is important to take into account when used as a biomarker for other neurodegenerative diseases such as Alzheimer’s disease." (PMID 30526557, 2018). "But also levels of synaptopodin, synaptophysin, synaptotagmins, neurogranin and GAP43 were lower in patients with Alzheimer's disease than in cognitively normal controls." (PMID 28912682, 2017). "This interaction was driven by a negative association between GAP-43 and episodic memory performance in the Alzheimer’s disease continuum group, whereas this association was null in the no Alzheimer’s disease pathology group." (PMID 39995657, 2025). "The relationship between CSF GAP-43 and episodic memory performance varied by AT(N) group status, suggesting a compounded effect of Alzheimer’s disease pathology and CSF GAP-43 on episodic memory performance in older adults in the Alzheimer’s disease continuum group." (PMID 39995657, 2025).
Alzheimer disease (continued). "Likewise, in an explorative study involving 441 human samples of lumbar CSF taken antemortem and ventricular samples collected postmortem, CSF GAP-43 was elevated in two cohorts of preclinical and clinical Alzheimer’s disease matched to healthy controls." (PMID 33578866, 2021). "CSF GAP-43 levels are increased in Alzheimer’s disease patients compared with other neurodegenerative disorders such as Parkinson’s disease and frontotemporal dementia and may be useful in the differential diagnosis of the disease." (PMID 33578866, 2021). "The level of CSF GAP-43 has been demonstrated to be elevated in Alzheimer’s disease and may be valuable in early disease detection." (PMID 33578866, 2021). "However, in Alzheimer’s disease (AD) reduction of neuronal GAP-43 mRNA and GAP-43 protein has been linked to memory dysfunction." (PMID 31888192, 2019). "Thus, the determination of CSF GAP-43 could possibly be of great significance in prospective tests for Alzheimer’s disease." (PMID 33578866, 2021). "Post hoc simple slopes analysis confirmed that CSF GAP-43 was negatively associated with episodic memory performance in the Alzheimer’s disease continuum group [95% confidence interval (CI) (−0.28, −0.12)] but not in the no Alzheimer’s disease pathology or SNAP groups." (PMID 39995657, 2025). "Both SNAP and Alzheimer’s disease continuum groups had greater CSF p-tau (181P) and CSF GAP-43 levels relative to the no Alzheimer’s disease pathology group." (PMID 39995657, 2025). "Intriguingly, there is a specific reduction in synaptophysin levels at the earliest stages of Alzheimer’s disease with no change in the levels of other presynaptic proteins such as synaptotagmin-1 or GAP-43." (PMID 26871701, 2016). "Our previous work using the Alzheimer’s Disease Neuroimaging Initiative (ADNI) demonstrated a negative relationship between CSF GAP-43 and episodic memory performance, but not executive function performance, independent of other biomarkers of neuronal dysfunction." (PMID 40993981, 2025). "They revealed that the presynaptic (synaptosomal-associated protein 25 (SNAP25), growth associated protein 43 (GAP43)) and postsynaptic markers (Ng) are elevated in CSF in early Alzheimer’s disease, i.e., in Aβ-positive individuals without evidence of tau pathology." (PMID 39769345, 2024). "In this present study, we mainly investigated the effects of CSF GAP-43 on cognitive impairment and whether the roles of GAP-43 were related to APOE ε4 status among cognitively normal (CN) controls, MCI and AD participants from the Alzheimer’s Disease Neuroimaging Initiative (ADNI) database." (PMID 36611808, 2022).
Cognitive impairment (25 papers, 2016 to 2025). Abnormal cognition is characterized by deficits in thinking, reasoning, or remembering. "We observed, in TRIAD and ADNI combined, that pTau181 acted as a mediator in the association of sTREM2 with the presynaptic marker GAP43 in the presence of Aβ positivity and with the postsynaptic marker Ng in the additional presence of cognitive impairment." (PMID 39184102, 2024). "Additionally, elevated GAP-43 levels can serve as early biomarkers for brain health, identifying individuals at lower risk for cognitive impairments." (PMID 39215335, 2024). "Our findings are consistent with prior studies showing higher SNAP-25, synaptotagmin-1, GAP-43, and neurogranin levels in CSF are associated with cognitive impairment in AD, which may be linked to synapse degeneration in the brain." (PMID 38299587, 2024). "Besides, CSF GAP-43 levels were also associated with cognitive deficits and neuroimaging finds both at baseline and during longitudinal follow up." (PMID 36253408, 2022). "Growth associated protein 43 (GAP43), neurogranin, synaptotagmins, Rab3A, and synaptosome associated protein 25 in neuronal-derived exosomes are expected to serve as blood biomarkers for AD and mild cognitive impairment." (PMID 34588957, 2021). "In conclusion, this study showed that XFZYD could upregulate LTP associated NMDAR/CaMKII/GAP-43 pathway, subsequently ameliorate cognitive deficit after TBI." (PMID 29069769, 2017). "Geniposidic acid (CHEBI:5301) has been shown to alleviate cognitive impairment in AD mice by upregulating GAP43 through the PI3K/AKT signalling pathway in mouse models." (PMID 40855644, 2025). "In this study, we aimed to observe the association of white matter (WM) features detected by diffusion tensor imaging (DTI) with the cerebrospinal fluid (CSF) level of GAP-43 in patients with cognitive impairment." (PMID 40831513, 2025). "Scientific studies suggest that exosomal proteins, including GAP43, can predict AD 5–7 years before the onset of cognitive impairment." (PMID 40855644, 2025). "Infarct volume, cerebral edema, neurological deficits, cognitive impairment, and the level of Synaptophysin (SYP)、Growth associated protein-43 (GAP43) and neuronal nuclear antigen (NeuN) levels were measured to evaluate the effect of nicorandil." (PMID 33497397, 2021). "In this study, we aimed to evaluate the potential association between findings in WM tracts and the CSF level of GAP-43 in patients with AD spectrum to observe the efficacy of GAP-43 as a reliable biomarker in the early detection of patients with cognitive impairment." (PMID 40831513, 2025). "Likewise, synaptic proteins such as PSD95, synaptophysin, and GAP43 are closely related to cortical atrophy and cognitive impairment in dementia." (PMID 40868282, 2025). "Effect on MISO‐induced cognitive impairment could be partially explained by the downregulation of GAP‐43 expression." (PMID 38945806, 2024). "A recent Chinese study revealed that exosomal SNAP25, GAP43, neurogranin, and synaptotagmin-1, combined with APOE ε4 status, improved diagnostic accuracy (AUC = 0.88), acting as a useful biomarkers panel for the prediction of AD five to seven years before cognitive impairment." (PMID 35360215, 2022). "Another study evaluating cognitive decline using the Functional Activities Questionnaire (FAQ) evaluation demonstrated a significant correlation between the baseline CSF levels of GAP-43 and FAQ scores among patients with cognitive impairment." (PMID 40831513, 2025). "GAP-43 and BDNF reduction in aged 5XFAD mice accelerates AD pathologies and triggers cognitive deficits." (PMID 37143467, 2023). "Levetiracetam for treatment of retinopathy as well as for the repair of convulsant- induced cognitive impairment directly signals through the PKC/GAP-43 signaling pathway." (PMID 33015061, 2020).
Cognitive impairment (continued). "To investigate whether increases in Gap43 and Snap25 could alleviate the cognitive impairment of 5×FAD, we designed an EV-based system to overexpress Gap43 and Snap25 in the neural cells of the 5×FAD mouse brain." (PMID 38528511, 2024). "Our results are consistent with the notion that anesthetic-induced reduction in GAP43 and PSD 95 may lead to decreased neuroplasticity and cognitive impairments in developing brain." (PMID 29773978, 2018).